SOX2 (SRY-box transcription factor 2)
Diseases named in the same sentence as SOX2 in open-access papers (continued):
Sharing a sentence is not in itself a finding about the gene and the disease.
tumor (continued). "SOX2 is an important marker for the promotion of tumor initiation and proliferation and participates in tumor metastasis." (PMID 31921660, 2019). "b, Representative and quantification of H&E and immunostaining (scale bar: 100 μm) of METTL3, SOX2, and EpCAM in subcutaneous tumor models of METTL3 knockdown and control SW620 and HCT116 cells." (PMID 31230592, 2019). "CQ and 3-MA decreased the tumor spheroid-forming potential and the expression of SOX2 in CT26Flag−CAGE1 cells." (PMID 31799196, 2019). "This strategy allowed independent monitoring by bioluminescence imaging (BLI) and confocal microscopy, of either the whole tumor population or the subpopulation of tumor cells with active GSC promoters CD133 or OCTA4/SOX2." (PMID 31267022, 2019). "Recently, we have shown that CDK1 plays a critical role in stochastic stemness and tumor initiation potential through regulating SOX2 phosphorylation in multiple cancer types." (PMID 31080551, 2019). "Obvious nuclear staining of TAZ and SOX2 was detected in cancerous cells while much less staining of SOX2 or cytoplasmic staining of TAZ was identified in non-tumor oral epithelial cells." (PMID 31399556, 2019). "Western blot showed that FAM289 increased the expression of stemness factors in U251 cell tumor-sphere, including SOX2, OCT4, and c-Myc, whereas FAM289 knockdown dramatically decreased its stemness expression in U87-MG cell tumor-sphere." (PMID 31492191, 2019). "While GCV treatment in vitro directly targets dividing CD133+ and OCT4/SOX2+ U87 cells, other replicating neighboring tumor cells can also be indirectly killed by a bystander effect." (PMID 31267022, 2019). "To determine the role of SOX2/OCT4-overexpressing CSCs in tumor initiation and recurrence, we used our SORE6 construct to express a suicide gene in PC3 cells." (PMID 31500347, 2019). "Sox2+ cells thus included glial and neural-progenitor-like subsets that varied in differentiation, and tumor-derived Sox2+ astrocytic cells tended to be undifferentiated." (PMID 31863004, 2019). "In other tumor types, it has been reported that SOX2 antagonizes signals promoting differentiation to maintain stemness in CSC subpopulations." (PMID 30823625, 2019). "The validation for GSCs enrichments is based on the combinatorial expression of cell surface markers (CD133, CD44, CD15), intracellular stem cell markers (Nestin, Sox2) and most importantly key stem cells features such as self-renewal and tumor initiation." (PMID 30895167, 2019). "In contrast, patients with low expression of GLI2 and SOX2 in the tumor had <60% of chance of cancer relapse." (PMID 30382189, 2019). "Expression of SOX2 was significantly higher in adjacent non-tumor as compared to tumor tissue (P=0.04)." (PMID 31244283, 2019). "It has been reported that Krt5+ and Sox2+ basal progenitors can act as the cellular origin for murine foregut tumor formation." (PMID 31110179, 2019). "The results of immunohistochemistry showed that β‐catenin and Sox‐2 expression was downregulated in tumour tissues harvested from the C3aR siRNA group." (PMID 30825266, 2019). "In vitro and in vivo, loss‐of‐function experiments showed that lncRNA SNHG20 knockdown inhibited proliferative ability, mammosphere‐forming ability, ALDH1 expression, stem factors (LIN28, Nanog, Oct4, SOX2) and tumour growth." (PMID 30394668, 2019). "The notion that BMP4 enforces tumor dormancy is supported by its ability to block in-vitro tumor sphere formation, to diminish the expression of Nanog, Sox2, and Taz, and increase that of GATA3." (PMID 31547567, 2019). "We showed that pacritinib treatment significantly reduced cell viability and colony/tumor sphere formation in association with reduced levels of STAT3, Sox2, PDCD4, and miR-21; it also reduced the ability to generate M2 GAMs." (PMID 31269723, 2019). "In the study group, positive SOX2 expression in the nucleus of the tumor cells was observed in 38/60 (63.3%) cases." (PMID 31508790, 2019).
tumor (continued). "The overexpression of SOX2 in tumor cells implies that SOX2 induces stemness in cells that have undergone genotoxic damage." (PMID 31508790, 2019). "While several genes within this amplicon have been implicated in neoplastic transformation, such as SOX2, PI3KCA and ECT2, the potential role of ST6Gal-I in the tumor-promoting activity of the 3q26 amplicon has gone unnoticed." (PMID 31610800, 2019). "Monitoring of PLuc activity showed an increase in tumor growth by days 63 (CD133) and 77 (OCT4/SOX2), while tumor growth remained inhibited in animals under continued GCV treatment." (PMID 31267022, 2019). "ALDH has been linked to confer therapy resistance and tumor prevalence via modulating the expression of PI3K (phosphoinositide 3-kinase) and SOX2 (SRY-box 2) signaling cascades." (PMID 31030466, 2019). "Several transcription factors, including BMI1, LGR5, NANOG, OCT4, and SOX2, are upregulated in various cancer types and promote stemness maintenance, local tumor invasion, and distant metastasis." (PMID 30866999, 2019). "Similar to human MBs,4 we showed that a minor cell population in tumor lesions—including many Sox2+ cells—expressed Olig2 protein." (PMID 31763624, 2019). "In this study, they show that quiescent tumor cells evade surveillance and elimination of metastatic seeds by NK cells and that Sex determining region Y-box 2 (SOX2) and SOX9 transcription factors are essential for CSCs survival and metastatic outgrowth." (PMID 30847298, 2019). "We found pacritinib treatment suppressed cell viability and colony/tumor sphere formation in association with decreased expression of STAT3, Sox2, PDCD4, and miR-21-5p and increased GFAP expression." (PMID 31269723, 2019). "High expression of miR-638 inhibits the proliferation, invasion, and angiogenesis of HCC cells to exert tumor suppression effects by inhibiting sex determining region Y-Box 2 (SOX2) or reducing intracellular oxidative stress status." (PMID 31815633, 2019). "The identification of subgroups within the Sox2+ population, including vismodegib-resistant Sox2+ stem-like cell types, extends the prior finding that Sox2+ cells are tumor propagating cells that can repopulate tumors after vismodegib therapy." (PMID 31863004, 2019). "Immunostaining of cryosections against the stem cell markers nestin, SOX2 and Oct4 suggested that the spheroids contained a population of stem-like tumor cells." (PMID 31227783, 2019). "Sox2 activity propels tumor cell migration and invasion, self-renewal, tumor initiating capacity, and chemoresistance." (PMID 31610800, 2019). "The mRNA expression of the putative tumor stem cell markers SOX2, Nanog, CD44, ALDH1, c-myc, and Oct4 was analyzed by qPCR." (PMID 30539198, 2019). "Fox example, Dickkopf-related protein 1 (DKK1), induced by SOX2, positively regulates myeloid-derived suppressor cells in the tumor microenvironment and provides metastatic latency and immune evasion in lung cancer by protecting cells from NK cells." (PMID 31080551, 2019). "Bulk transcriptomic analysis of eGFP+ tumor cells from these mice showed upregulation of specific stem cell markers, including Sox2, Gfap, Olig1, Olig2, Blbp (Fabp7) and Pdgfra31." (PMID 31863004, 2019). "Then the effect of SOX2 on tumor metastasis in vivo was performed by metastatic model of human TNBC cells in nude mice." (PMID 30186173, 2018). "Similar to BCL11A we found that SOX2-KD cells had a significantly reduced colony and tumour formation abilities." (PMID 30127402, 2018).
tumor (continued). "We show that BCL11A upregulation leads to early stages of tumour development in the mouse and is critical for tumour maintenance even in the presence of SOX2." (PMID 30127402, 2018). "In order to confirm tumor sphere inhibition by nobiletin, we isolated RNA from the spheres and determine the expression of the SOX2, OCT4, and NANOG genes, which are considered stem cell markers." (PMID 29914089, 2018). "For example, exosomes secreted by preadipocytes promote early breast cancer formation and tumor growth in vivo by transporting the transcription factors SOX2 and SOX9." (PMID 30344611, 2018). "In another study, it was found that Sox2 expression correlates with high histologic grade, large tumor size and a high proliferation index." (PMID 29401647, 2018). "In other tumors, it has also been found that SOX2 induces dedifferentiation of tumor cells and confers a stem cell-like phenotype." (PMID 30344611, 2018). "Using immunohistochemistry assay we found a decreased expression of SOX2 in Lenti-sh-DNMT1 or 5-aza-dC treated tumor xenografts." (PMID 29721170, 2018). "Consistent with the previous experiment results, the expression of SOX2 protein in mice tumour was significantly down‐regulated after stable transfection with sh‐MALAT1 or AgomiR‐129 mimics." (PMID 29808528, 2018). "The integration of exogenous genes encoding transcription factors (OCT4, SOX2, C-MYC, and KLF4) can be detected in iPSCs, raising concern about the risk of mutagenesis and tumor formation." (PMID 30460090, 2018). "Because of the tenacious metastatic behavior of ACC, this study aims to elucidate the expression and clinical relevance of SOX2 in this rare but aggressive tumor entity with dismal survival rates for many patients." (PMID 29596469, 2018). "These molecular networks with reported functionality in tumor progression and treatment resistance prompted us to investigate protein co-expression levels and patterns of Sox2, EpCAM and vimentin in HNSCC." (PMID 30275505, 2018). "ACTL6A has been reported to regulate the activity of many oncogenes, including WWC, SOX2, c-Myc, which all have important roles in promoting tumor progression." (PMID 29725063, 2018). "To confirm these results, we carried out immunohistochemical (IHC) analysis of six of the eight tumors in our cohort and found widespread expression of SOX2 protein in every tumor." (PMID 30041684, 2018). "Analysis of HPV infection status detected HPV-positive tumours in 98/313 (31.31%) patients and HPV-negative tumours in 215/313 (68.69%) patients in the SOX2-high subgroup." (PMID 29374236, 2018). "To confirm tumor sphere formation, we analyzed the expression levels of SOX2, OCT4, and NANOG, which are considered to be stem cell markers." (PMID 29914089, 2018). "The identities of both primarily cultured p-GBM tumor cells were confirmed by analyzing the expression of specific markers (sox2, nestin for GBM neural stem cells; GFAP, NeuN for differentiated GBM tumor cells)." (PMID 29527330, 2018). "Remarkably, amongst the top hits we recovered SOX9, a key stem factor reported to be co-expressed in SOX2+ tumor-initiating SCCs37,38." (PMID 30467425, 2018). "SOX21, the counteracting partner of SOX2, functions as a tumour suppressor during gliomagenesis by negatively regulating SOX2." (PMID 30382873, 2018). "SOX2 appears to be able to contribute to both tumour initiation and progression by directly regulating genes involved in cancer functions such as stemness, proliferation, survival and invasion." (PMID 29506506, 2018). "High SOX2 expression was also correlated with better survival in other tumor entities despite the well-established function of SOX2 in tumor-relevant processes." (PMID 29596469, 2018). "SOX2 was controversial in GC tissues; it was reported as a tumor promoter to activate AKT signaling on the one hand, and SOX2 was also detected as a protective factor to inhibit proliferation and metastasis." (PMID 29921304, 2018).
tumor (continued). "Knockdown of Sox2 expression in SCLC with Sox2 amplification resulted in inhibition of tumor growth." (PMID 30060526, 2018). "The similar expression levels of stemness markers, such as Nanog, OCT3/4 and SOX2, observed both in NB-MSCs and BM-MSCs, suggest that NB-MSCs, even when derived from the tissue/tumor microenvironment, maintain BM-MSC multipotentiality." (PMID 30482160, 2018). "In line with this assumption, the prognostic value of SOX2 expression differs between distinct tumor entities." (PMID 29596469, 2018). "Expression of the stem cell factors SOX2, OCT4, NANOG, and MYC has been linked to tumor malignancy in several cancers." (PMID 30510261, 2018). "In this study, we grew a subpopulation of RCC cells as tumour spheres with higher levels of stemness‐related genes, such as Oct4, Sox2 and Nanog." (PMID 30246456, 2018). "SOX2 is a known oncogene expressed in a variety of SCCs, and is thought to be essential for the maintenance of tumor-initiating properties." (PMID 30467425, 2018). "SOX2+ cells were seen in all tumor samples, and the median labeling index of SOX2 in this cohort was 0.87, suggesting that the vast majority of transformed HGG cells are SOX2+." (PMID 30041684, 2018). "Cells expressing Notch displayed higher tumor initiation capacity compared with Notch− cells, and exhibited self-renewal capacity by increasing the expression of stem cell markers such as Oct4, Sox2, and CD4438." (PMID 29410396, 2018). "We also performed limiting dilution assay (LDA) to assess the tumor-initiating capabilities of SOX2+ positive cells from HN120Pri, HN137Pri, and HN137PCR, as well as from the SOX2− populations in HN120PCR." (PMID 30467425, 2018). "For example, one finding shows that TP63, TP73, and SOX2 expression in tumor tissues of early, middle, and late stages is higher than that in the adjacent non-tumorous tissues." (PMID 29340250, 2018). "In the majority of these cancers, SOX2 has been found to have increased expression or gene amplification in tumor tissues." (PMID 30466459, 2018). "SOX2 contributes to the acquisition of an aggressive oxidative tumor phenotype, endowed with enhanced drug resistance and metastatic ability." (PMID 30466459, 2018). "Concerning EpCAM, it was shown that EpCAM and transcription factors Oct4, Nanog, Sox2 and c-Myc are concomitantly expressed in colon TICs and EpCAM overexpression enhanced tumor sphere formation." (PMID 29652830, 2018). "QSOX1, SOX2, SLUG, STF1 were all associated to a more benign course of disease, suggesting control of tumor initiation and cancer stem-cell functions versus epithelial-mesenchimal transition in NSCLC." (PMID 30473748, 2018). "Dedifferentiation of a tumor by hypoxia helps in the maintenance of stem like properties of tumor cells by the expression of genes like Oct4, SOX-2 and Nanog." (PMID 29719610, 2018). "We observed that both SOX2 and MYC expression were associated with high grade tumor histology, while OCT4 expression correlated with low grade histology." (PMID 30510261, 2018). "A previous study showed that Slug directly induces Sox2 activation and increase tumor-initiating cell properties." (PMID 30551687, 2018). "Most stem cell markers were expressed at only a low level in the both core and periphery of the tumor, except for Sox2 and CD44, which showed high expression in both sites, and CXCR4, which showed slightly higher expression in the periphery." (PMID 30210550, 2018). "Nonetheless, EpCAM and Sox2 possessed prognostic value, even under these testing conditions and in the presence of the primary tumor throughout the observation period (Göttingen cohort)." (PMID 30275505, 2018). "CSCs have been characterized with different specific cell surface markers such as Sox2 and Nanog, the major stemness-related genes, and have been considered as the key factor for tumor initiation and progression." (PMID 29416638, 2018).
tumor (continued). "We next analysed the effect of forced expression of BRACHYURY or/and SOX2 on cell invasiveness in vitro using a tumour cell dissemination assay that we established previously." (PMID 30453543, 2018). "To further evaluate the role of SOX2 in tumor formation and growth in vivo, we adopted xenograft model of human TNBC cells in nude mice." (PMID 30186173, 2018). "Doxorubicin alone was sufficient to reduce primary tumor growth but prior exposure to doxorubicin was required for T12 to inhibit metastases formation and to reduce Sox2 expression." (PMID 29541394, 2018). "The q-RT-PCR results demonstrated that the effects of si-hVDAC1 on the expression of the CSC transcription factors Oct3/4, SOX2 and Nanog were highest in A549-derived tumours, where expression levels were decreased 15–45-fold." (PMID 30544833, 2018). "In adults, SOX2 is re-expressed in cancer cells, particularly in the early stages of tumor development, suggesting its involvement in tumor-initiating events." (PMID 29963265, 2018). "Sox2-depleted OS cells reduced sphere formation and attenuated tumor formation in the xenograft assay." (PMID 29991717, 2018). "Significantly, SOX2 knockdown leads to 4.4 and 4.7 fold decreases in the volume and weight of tumour, respectively (n = 5)." (PMID 28288641, 2017). "In the GFAP positive tumour surrounding brain parenchyma of aCP, several Sox2+ cells showed co-expression of Olig2." (PMID 29158570, 2017). "We then analyzed the correlation between the percentage of SOX2-positive cells from tumor samples isolated from 25 patients and the presence of metastasis in these patients." (PMID 28934267, 2017). "CK2 activity is required for cancer stem cell-like cell maintenance, tumor sphere formation and proliferation, and for the expression of cancer stem cell genes and proteins (e.g., Nanog, Oct4, and Sox2) in HNSCC." (PMID 28134850, 2017). "The high frequency of tumor emboli found in Sox2-overexpressing tumors indicated that Sox2-overexpressing cells were more aggressive than the cells with low Sox2 expression levels." (PMID 29228716, 2017). "Initially, we determined that elevating SOX2 with the aid of an inducible promoter in one of these PDAC cell lines dramatically reduced tumor growth." (PMID 28388544, 2017). "To gain more information about the properties of Sox2+ and Sox9+ cells located near the aCP, we decided to perform double-immunofluorescence staining of selected tumour samples using antibodies against Sox2 or Sox9 and Olig2." (PMID 29158570, 2017). "Taken together, this study has shown that the expression of both SEC62 and SOX2 shows differences between the primary tumor and lymph node metastases of HNSCC patients and between the lymph node metastases of HNSCC and CUP patients." (PMID 28002801, 2017). "The first delves into the expression and function of SOX2 in cancer focusing on the connection between SOX2 levels and tumor grade as well as patient survival." (PMID 28388544, 2017). "This striking difference was also reflected in the miR-145 target genes, Oct4/Sox2/Fascin1 which were all upregulated in the MCPyV-positive tumour samples." (PMID 29348831, 2017). "Most of the well differentiated tumor cells in TN presented relative low Sox2 expression and showed an elongated shape." (PMID 29228716, 2017). "Xenografted tumors burden of Sox2-overexpressing cells showed high microvessel density and tumor emboli located in capillaries or vessel-like structures." (PMID 29228716, 2017). "Increased expression of SOX2 protein was also found in the tumor-bearing pituitary of the dopamine receptor D2 knock-out (Drd2−/−) mouse model." (PMID 29255445, 2017). "For targeting stem cell elimination, tumor formation is also driven by the expression of some genes involved in “stemness”, including Oct4, Nanog, and Sox2." (PMID 27793013, 2017).